PLEKHA8 (pleckstrin homology domain containing A8)
Description:
Mediates the non-vesicular transport of glucosylceramide (GlcCer) from the trans-Golgi network (TGN) to the plasma membrane, playing a pivotal role in the synthesis of complex glycosphingolipids; binding of both phosphatidylinositol 4-phosphate (PIP) and ARF1 are essential for this GlcCer transfer ability. Also functions as a cargo transport protein required for apical transport from the Golgi complex, including transport of AQP2 from the TGN to sites of AQP2 phosphorylation. Additionally required for primary cilium formation, possibly by being involved in the transport of raft lipids to the apical membrane, and for membrane tubulation (By similarity).
Synonyms: FAPP2; MGC3358
Tractability: Small molecule: a structure with a bound ligand is known. Antibody: UniProt places it where antibodies can reach, with high confidence. PROTAC: ubiquitination databases record sites on it.
Gene: Protein-coding gene on chromosome 7 (30,027,404 to 30,130,483, forward strand). Ensembl gene ENSG00000106086.
Subcellular location: Golgi apparatus, trans-Golgi network membrane
Subcellular location (Human Protein Atlas): Golgi apparatus; Nucleoplasm
Pathways (Reactome):
Metabolism: Synthesis of PIPs at the plasma membrane
Transport of small molecules: Glycosphingolipid transport
Gene Ontology:
Molecular function: ceramide binding; cerebroside transfer activity; glycolipid binding; glycolipid transfer activity; molecular carrier activity; phosphatidylinositol-4-phosphate binding; protein binding; ceramide 1-phosphate binding; glycosphingolipid binding; lipid transfer activity; sphingolipid transfer activity
Biological process: ER to Golgi ceramide transport; globoside biosynthetic process; glycolipid transport; lipid transport; intermembrane lipid transfer; phosphatidylinositol biosynthetic process
Cellular component: nucleoplasm; trans-Golgi network; cytosol; Golgi membrane; cis-Golgi network membrane; cytoplasm; Golgi apparatus
Genetic constraint (gnomAD): Loss-of-function variants: 30 observed, 53.72 expected, observed/expected ratio (o/e) 0.56, 90% interval 0.42 to 0.76. The upper end of that interval is the gene's LOEUF score, 0.76, which puts it in group 3 of 6, group 1 being the genes least tolerant of losing a copy. Missense variants: 474 observed, 569.95 expected, observed/expected ratio (o/e) 0.83, 90% interval 0.77 to 0.9. Synonymous variants: 201 observed, 203.63 expected, observed/expected ratio (o/e) 0.99, 90% interval 0.88 to 1.11.
Homologues: Orthologues: chimpanzee PLEKHA8 (99% identical), macaque PLEKHA8 (99% identical), guinea pig PLEKHA8 (94% identical), mouse Plekha8 (93% identical), dog PLEKHA8 (93% identical), rat Plekha8 (92% identical), pig PLEKHA8 (88% identical), rabbit PLEKHA8 (85% identical), tropical clawed frog plekha8 (67% identical), zebrafish plekha8 (61% identical), Caenorhabditis elegans F49D11.10 (16% identical), Caenorhabditis elegans Y82E9BR.14 (13% identical), and 2 more. Paralogues in human: PLEKHA3 (29% identical), CERT1 (21% identical), GLTP (15% identical), GLTPD2 (11% identical), CPTP (9% identical).
Diseases named in the same sentence as PLEKHA8 in open-access papers:
PLEKHA8 is named in the same sentence as 7 diseases in open-access papers, as found by Europe PMC text mining. Sharing a sentence is not in itself a finding about the gene and the disease. The quoted sentences say what the papers report.
liver cancer (2 papers, 2021 to 2025). An epithelial or non-epithelial malignant neoplasm that arises from the liver. "Experimental validation showed that PLEKHA8P1 and its parental gene PLEKHA8, a known oncogene, promote tumor progression in colorectal and liver cancers." (PMID 40556338, 2025). "In order to establish the relationship between the pseudogene-parent pair alongside functional interrogation of PLEKHA8 in liver cancer cells, we constructed a PLEKHA8-overexpression plasmid." (PMID 34299245, 2021). "To test the relationship of pseudogene and its parental gene, we examined the gene expression of a parent gene, PLEKHA8 in primary liver tumors." (PMID 34299245, 2021). "Taken together, these findings indicate that PLEKHA8P1 and its parent gene, PLEKHA8, promote tumorigenesis in liver cancer and PLEKHA8P1 demonstrates a better prognostic value than its parental gene." (PMID 34299245, 2021). "Significant upregulation was found in primary liver tumors, suggesting PLEKHA8P1 may promote liver cancer progression by up-regulating its parent gene, PLEKHA8." (PMID 34299245, 2021).
colon cancer (1 paper, 2021). "We also noted with considerable interest that PLEKHA8 parental gene promotes tumor progression, as observed in colon cancer and HCC cell lines (HepG2, MHCC97H, SNU-449) and xenograft tumor models, by enhancing Wnt/β-catenin signaling, one of the oncogenic pathways often targeted for HCC treatment." (PMID 34299245, 2021).
cancer (2 papers, 2021). A tumor composed of atypical neoplastic, often pleomorphic cells that invade other tissues. "We were able to confirm that PLEKHA8 exhibits oncogenic features through cell survival analysis post-PLEKHA8 overexpression (OE), whereby increased cancer cell proliferation is observed in PLEKHA8-OE groups." (PMID 34299245, 2021). "Studies have shown that the parental gene PLEKHA8 plays an oncogenic role wherein it promotes cancer cell growth, while its knockdown displays opposite phenotypes." (PMID 34299245, 2021). "Given this indication of positive correlation between PLEKHA8P1 and PLEKHA8, we were able to reason that the pseudogene affects cancer cell growth by positive regulation over its parental gene, one which has been revealed to hold oncogenic properties." (PMID 34299245, 2021). "Though initially characterized as an integral member in membrane trafficking, studies have revealed the tumorigenic role of PLEKHA8 in various cancers, including HCC by enhancing the Wnt/β-catenin pathway." (PMID 34299245, 2021). "Our study has thus confirmed cancer-related functions of PLEKHA8, and laid the groundwork for identification and validation of oncogenic pseudogene-derived lncRNA that shows potential as a novel therapeutic target in circumventing chemoresistance induced by 5-FU." (PMID 34299245, 2021). "Two antigens (n = 2/50, PLEKHA8 and PRM2) showed abundant uniform reactivity across all healthy, all benign and virtually all cancer samples (n = 78/80, n = 79/80 respectively) and were excluded from subsequent analyses." (PMID 34681879, 2021).
tumor (2 papers, 2021 to 2025). "Though RNAseq expression data indicated that both PLEKHA8P1 and PLEKHA8 are up-regulated in tumor samples, we used qRT-PCR to confirm in vitro the manner of correlation between their expression levels." (PMID 34299245, 2021). "In addition, its parental gene PLEKHA8 has been previously characterized as on oncogene, and our analysis reflects the possibility, since PLEKHA8 is up-regulated in tumor samples and also predicts poor prognosis for high-expression patients." (PMID 34299245, 2021). "Our data are thus indicative of a PLEKHA8P1-PLEKHA8 axis in modulating chemoresistance, with PLEKHA8P1 as a possible ceRNA for miRNAs that inhibit PLEKHA8, which in turn promotes tumor progression through Wnt/β-catenin signaling." (PMID 34299245, 2021).
PLEKHA8 also shares sentences with these, for which no sentence is quoted: atherosclerosis (1 paper); heart failure (1); inflammatory bowel disease (1).